BDNF (brain derived neurotrophic factor)
Diseases named in the same sentence as BDNF in open-access papers (continued):
Sharing a sentence is not in itself a finding about the gene and the disease.
schizophrenia (continued). "Moreover, studies performed on post-mortem brain tissue of patients with psychiatric disorders such as schizophrenia (SZ), bipolar disorder (BD), and major depressive disorder (MDD) also evidenced lower BDNF levels in brain regions involved in mnemogenic processes, such as the hippocampus." (PMID 31906013, 2019). "Given that BDNF is involved in synapse regulation, learning and memory, BDNF deficits seen in schizophrenia may lead to negative and cognitive symptoms." (PMID 31185023, 2019). "In conclusion, our preliminary data suggests that serum BDNF level maybe not a suitable biomarker for DS, despite its significantly lower levels in the schizophrenia patients." (PMID 31420036, 2019). "Further, reduced serum BDNF levels may be related with weight gain in female but not in male patients with schizophrenia under long-term antipsychotic treatment." (PMID 32116676, 2019). "In conclusion, an intermittent normobaric hypoxia regimen that successfully increases the BDNF levels may offer a non-pharmacological treatment to patients with schizophrenia." (PMID 30327610, 2018). "Studies utilizing psychiatric conditions have reported clinical improvements with increased serum BDNF levels following non-pharmacological approaches, including exercise, computer-assisted cognitive enhancement in schizophrenia and mindfulness clinical trials in bipolar-disorder." (PMID 29568518, 2018). "BDNF levels in patients with schizophrenia with and without metabolic syndrome." (PMID 28562580, 2017). "There may be different reasons for the absence of a linear relationshipbetween blood BDNF and brain activity in schizophrenia." (PMID 25162472, 2015). "Indeed, in peoplewith schizophrenia, as plasma BDNF levels increased, no parallel change in task-relatedbrain activity was detected in the cortical or subcortical regions examined." (PMID 25162472, 2015). "The lack of relationship betweenplasma BDNF and task-related brain activity in patients suggests that circulating bloodBDNF may not be indicative of learning-dependent brain activity in schizophrenia." (PMID 25162472, 2015). "So far, independent replication approaches regarding BDNF, DLGAP3, and GRIN2B have not been conducted and further studies are needed to untangle the interplay of pharmacological and genetic risk factors for OCS in schizophrenia." (PMID 26556409, 2014). "In short, it is not elucidated whether serum BDNF levels reflect or not depressive factors in schizophrenia." (PMID 25538582, 2014). "As reviewed above, very few studies that have evaluated the symptom correlates of BDNF in schizophrenia suggest significant negative correlation between BDNF and positive symptoms as well as link between BDNF and certain brain regions that are shown to underlie the genesis of FRS." (PMID 23847552, 2013). "Moreover, evidence showed that peripheral BDNF synthesis or release is reduced during acute episodes of schizophrenia, although it is not known whether it is a pathologic or compensatory effect." (PMID 37685795, 2023). "Thus, in a neurodevelopmental model of schizophrenia, e.g., in rats with a neonatal ibotenic lesion of the ventral HIP or in rats exposed to the MAM toxin during embryogenesis, decreases in BDNF mRNA and its protein were observed in both the PFC and HIP in adulthood." (PMID 35216241, 2022). "However, it should be noted that BDNF is not suggested as a specific marker for schizophrenia." (PMID 36387009, 2022). "Therefore, higher levels of BDNF in FEDN schizophrenia patients with depressive symptoms may be a compensatory response to reduced antioxidant status and pro-inflammatory imbalance in patients with first-episode schizophrenia." (PMID 35757201, 2022). "Additionally, low levels of serum BDNF may contribute to the positive symptoms of FEDN schizophrenia but not to depressive symptoms." (PMID 35757201, 2022).
schizophrenia (continued). "In addition, executive dysfunction in schizophrenia is also, in part, a consequence of increased oxidative stress, as illustrated peripherally by several molecular systems, such as glutathione/GSH and, centrally, via reduced neurotrophic factors, such as brain-derived neurotrophic factor (BDNF)." (PMID 34887622, 2021). "In addition, it should not be overlooked that BDNF levels are affected by lifestyle factors such as drug use, age, physical exercise, diet and stress, which may be significant for schizophrenia patients." (PMID 34763683, 2021). "Our results cannot be extended to patients with schizophrenia with other types of prominent symptoms (such as those with prominent negative symptoms or those with non-treatment-resistant schizophrenia) or to patients with another psychiatric condition that may have another baseline BDNF status." (PMID 34069556, 2021). "Thus, cerebral insulin resistance in schizophrenia may induce reduced signal transduction for gamma-aminobutyric acid (GABA), N-methyl-d-aspartic acid (NMDA), dopamine-D2 receptors, and reduced levels of brain-derived neurotrophic factor (BDNF)." (PMID 32121669, 2020). "Thus, the prefrontal cortex BDNF levels do not follow a normative linear age effect in schizophrenia patients with increasing age, which may represent a “floor effect” due to an earlier decline." (PMID 29896133, 2018). "Data regarding the measurement of BDNF levels pre and post ECT therapy in patients with schizophrenia are very limited without an extended follow-up period and evaluation of mental health change." (PMID 37685795, 2023). "No direct correlation was found between BDNF and MMSE in both individuals with schizophrenia and those with methamphetamine addiction." (PMID 37520481, 2023). "Although BDNF is not a disease-specific biomarker, it is considered as a potential biomarker having a very modest but significant relationship to cognitive functioning in schizophrenia, especially in chronic samples, that might be mediated by stress, early life trauma, insomnia and loneliness." (PMID 35873262, 2022). "Dysfunctional BDNF signaling in the PFC, but not in the hippocampus, results in the PFC-dependent cognitive deficits in the subchronic PCP-induced rodent model of schizophrenia." (PMID 35308288, 2022). "Peripheral BDNF is neither a sufficient measure of MDD severity, nor does it discriminate between MB, BPD and schizophrenia." (PMID 33255237, 2020). "A randomized, placebo-controlled trial of a combination of Lactobacillus rhamnosus and Bifidobacterium lactis Bb12 in schizophrenia did not change PANSS scores over the course of the 14 week trial, though a trend increase in plasma BDNF was observed." (PMID 32226399, 2020). "Alterations in BDNF are not specific to MDD and can serve as a state biomarker in MDD, BPD and schizophrenia." (PMID 33255237, 2020). "There was a non-significantpositive correlation between plasma BDNF level and daily CPZ equivalent dose in peoplewith schizophrenia (r = 0.36, p = 0.16)." (PMID 25162472, 2015). "However, the levels of BDNF and NURR1 mRNAs in the low inflammation schizophrenia group compared to low inflammation controls were not significantly different." (PMID 40335479, 2025). "Currently, however, we could not bring the MWA and BDNF into the binary logistic regression, as the MWA or BDNF may not be sufficient to predict schizophrenia accurately." (PMID 37234686, 2023). "Our own findings of a negative correlation between BDNF serum levels and FA values in the SLF of schizophrenia patients might reflect this dysfunctional neurotrophic mechanism." (PMID 32153434, 2020). "Sex specific effects of PCP on cognition, brain derived neurotrophic factor (BDNF), spine synapses and dopamine turnover in prefrontal cortex were found in the juvenile but not, adult monkey’s representing the primate PCP model of schizophrenia." (PMID 29020988, 2017).
schizophrenia (continued). "Note however that this model does not imply that reelin is the only link between PNS and schizophrenia, as other PNS-regulated genes like GAD67 and BDNF may also impact on the symptomatology of schizophrenia." (PMID 26968981, 2016). "The lack of significant correlations between BDNF, NGF-β, vitamin D, and other cognitive domains could be attributed to the complex interplay of various factors influencing cognitive function in schizophrenia, such as disease severity, medication status, and educational background." (PMID 40082848, 2025). "In addition, noradrenergic functions and BDNF were not related to the GAF scores of the present patients with chronic schizophrenia, indicating that both of the noradrenergic functions do not reflect the social activities of the chronic schizophrenia patients." (PMID 26770258, 2016). "It has been suggested that BDNF rs6265 genotype in hippocampus and inferior marginal medial prefrontal cortex may affect NMDA receptor-mediated neurotransmission and plasticity, which is related to the generation of positive or negative symptoms of schizophrenia." (PMID 36325525, 2022). "The negative correlation between the change in peripheral BDNF levels and the change in depressive symptoms observed in the present study implies that BDNF may be a mediator of the antidepressant effect induced by n−3 PUFA in patients with first-episode schizophrenia." (PMID 31098654, 2019).
Obesity (494 papers, 2007 to 2026). Accumulation of substantial excess body fat. "It is important to note that some populations with a higher risk of AD (e.g., those living with obesity or metabolic syndrome) have elevated resting levels of BDNF." (PMID 40405549, 2025). "Circulating BDNF levels are decreased in people with T2D independently of obesity and associated with impaired glucose homeostasis." (PMID 40171198, 2025). "Obesity is associated with chronic low-grade inflammation and metabolic dysregulation, which can impair myokine signaling pathways and reduce BDNF levels." (PMID 41277875, 2025). "Beyond these sociodemographic factors, we observed that genetic variants such as BDNF rs6265 had a greater impact on obesity in individuals with a lower energy intake, while their effects diminished in those with a higher energy intake." (PMID 40002356, 2025). "Previous research on obesity-related genetic variants such as brain-derived neurotrophic factor (BDNF) rs6265 has employed molecular docking to identify bioactive compounds influencing genetic risk." (PMID 40077791, 2025). "While genetic variants like BDNF rs6265 significantly influenced the obesity risk in individuals with a lower energy intake, their effects were negligible in the high-energy-intake groups." (PMID 40002356, 2025). "Elevated BDNF levels have been shown to promote satiety, while BDNF deficiency has been associated with impaired satiety, a factor that can contribute to the development of obesity." (PMID 41007867, 2025). "The intake of citrus fruits and green vegetables was inversely associated with obesity risk in participants carrying the BDNF rs6265 variant." (PMID 40002356, 2025). "Aging results in BDNF deficiency, inducing cognitive decline and increasing the vulnerability of middle-aged adults to obesity." (PMID 40724847, 2025). "Significant association between the presence of rs6265 in BDNF (Val66Met SNP) and obesity in ethnically homogenous groups of healthy Caucasian children and adolescents, as well as Chinese children." (PMID 40697550, 2025). "BDNF is also known to play a role in the regulation of food intake, thus, low BDNF levels have been associated with obesity, insulin resistance, and other components of MS." (PMID 41187128, 2025). "People with obesity carrying some specific variants of the BDNF gene achieve greater weight loss after bariatric surgery." (PMID 40171198, 2025). "Notable secondary findings included associations between BDNF changes and improved glucose metabolism and beta cell function in adolescents with obesity." (PMID 40863762, 2025). "Substantial evidence suggests that BDNF signaling is associated with energy imbalance and severe obesity in both humans and rodents." (PMID 40697550, 2025). "FTO rs1421085 has been shown to interact with physical activity to modulate obesity risk in Caucasian populations, and BDNF rs6265 influences dietary preferences and satiety regulation." (PMID 40002356, 2025). "Our study highlights the importance of gene–diet interactions in obesity, particularly those involving the BDNF rs6265 variant." (PMID 40002356, 2025). "In the cohort, green vegetable and citrus fruit intake was inversely associated with obesity risk, particularly in individuals carrying the BDNF rs6265 variant, consistent with the molecular docking results." (PMID 40002356, 2025). "Variants in the gene brain‐derived nuclear factor (BDNF) have been consistently associated with childhood BMI and obesity." (PMID 41082226, 2025). "Third, obesity is associated with decreased levels of brain-derived neurotrophic factor (BDNF), a protein essential for neuronal development, plasticity, and survival." (PMID 40655479, 2025). "The deficiencies of BDNF in both liver and skeletal muscles contribute to obesity, highlighting a complex interaction among these organs that extends beyond the scope of this review." (PMID 39655343, 2024).
Obesity (continued). "Mutations in the BDNF gene have been associated with hyperphagia and obesity, while exogenous administration of BDNF has been shown to induce weight loss in animal models." (PMID 38673018, 2024). "Without adipocytic BDNF, the obese phenotype resulting from central BDNF deficiency cannot manifest, thus, the presence of adipocyte BDNF is necessary for expressing obesity due to central BDNF deficiency." (PMID 39655343, 2024). "The identification of BDNF as a key gene linked to obesity highlights its crucial role in metabolic regulation, affecting both the CNS and peripheral organs." (PMID 39655343, 2024). "The present study was the first to examine the effect of the BDNF polymorphism on HRQoL amongst youth with obesity." (PMID 38997217, 2024). "The role of circulating BDNF in neurological impairments associated with obesity has received considerable attention in the recent literature." (PMID 38785805, 2024). "Peripheral estrogen exerts autocrine and paracrine effects that contribute to increased body mass, alongside elevated BDNF and leptin levels, in the context of central BDNF deficiency— an occurrence referred to as "obesity protecting obesity"." (PMID 39655343, 2024). "Heterozygous BDNF or TrkB mutations cause overconsumption and massive obesity in animals and humans." (PMID 39443799, 2024). "Future rigorous large-scale studies with raw data available are imperatively needed to examine the associations between exercise and BDNF expression in the context of obesity." (PMID 38618555, 2024). "The oral buccal swab was performed for genotyping of FTO rs9939609, MC4R rs17782313, BDNF rs6265 and genetic risk of obesity was calculated." (PMID 38662725, 2024). "SNPs in or near these genes (rs9939609 for FTO, rs17782313 for MC4R, rs6265 for BDNF) are associated increased appetite or energy intake, through which the SNPs are suggested to increase the risk of obesity." (PMID 38662725, 2024). "Obesity is due to hyperphagia caused by the deletion of the BDNF gene (brain-derived neurotrophic factor)." (PMID 39600756, 2024). "As BDNF is known as a “metabolic factor,” BDNF impairments are closely associated with increased appetite, obesity, and T2DM." (PMID 38975245, 2024). "In aggregate, these findings and those of others strongly suggest that VMHBDNF neurons contribute significantly to the obesity associated with BDNF and TrkB mutations." (PMID 39443799, 2024). "Mutations of the genes encoding BDNF or TrkB, its receptor, cause extreme obesity in mice and humans, indicating that neurons that express these genes normally restrict food intake and weight gain." (PMID 39443799, 2024). "Estrogen deficiency is linked to obesity in over 43% of menopausal women, characterized by a central reduction of BDNF levels, while plasma BDNF remains unaffected." (PMID 39655343, 2024). "As BDNF mutations cause obesity, we initially set out to identify which BDNF neurons normally restrict overfeeding in animals fed a HPD." (PMID 39443799, 2024). "Mice and humans with mutations in BDNF or TrkB develop hyperappetitive obesity due to impaired hypothalamic anorexia and hypercompetitive signaling pathways." (PMID 38672461, 2024). "It was reported that mutations in the genes encoding BDNF and its receptor TrkB lead to severe obesity in humans." (PMID 38672461, 2024). "To date, only 1 disease-causing BDNF point mutation has been identified in humans in association with hyperphagia, obesity, hyperactivity and impaired cognitive function." (PMID 38019584, 2024). "Genetic mutations impacting BDNF or its receptor TrkB result in significant overeating and severe obesity in both humans and mice." (PMID 38026693, 2023). "Loss of FTO leads to the altered expression of several key components of the brain-derived neurotrophic factor pathway [BDNF, 13], which has been repeatedly linked to polygenic and mono-genetic obesity forms via several molecular mechanisms." (PMID 37223038, 2023).